ENSG00000274450
Synonyms: LOC124900456
Gene: Small nuclear RNA gene on chromosome 1 (146,862,729 to 146,862,845, reverse strand). Ensembl gene ENSG00000274450.
Gene Ontology:
Molecular function: pre-mRNA 5'-splice site binding; U4atac snRNA binding
Biological process: mRNA 5'-splice site recognition; spliceosomal tri-snRNP complex assembly
Cellular component: U6atac snRNP